SLC22A6 (solute carrier family 22 member 6)
Description:
Secondary active transporter that functions as a Na(+)- independent organic anion (OA)/dicarboxylate antiporter where the uptake of one molecule of OA into the cell is coupled with an efflux of one molecule of intracellular dicarboxylate such as 2-oxoglutarate or glutarate. Mediates the uptake of OA across the basolateral side of proximal tubule epithelial cells, thereby contributing to the renal elimination of endogenous OA from the systemic circulation into the urine. Functions as a biopterin transporters involved in the uptake and the secretion of coenzymes tetrahydrobiopterin (BH4), dihydrobiopterin (BH2) and sepiapterin to urine, thereby determining baseline levels of blood biopterins. Transports prostaglandin E2 (PGE2) and prostaglandin F2-alpha (PGF2-alpha) and may contribute to their renal excretion. Also mediates the uptake of cyclic nucleotides such as cAMP and cGMP. Involved in the transport of neuroactive tryptophan metabolites kynurenate (KYNA) and xanthurenate (XA) and may contribute to their secretion from the brain. May transport glutamate. Also involved in the disposition of uremic toxins and potentially toxic xenobiotics by the renal organic anion secretory pathway, helping reduce their undesired toxicological effects on the body. Uremic toxins include the indoxyl sulfate (IS), hippurate/N-benzoylglycine (HA), indole acetate (IA), 3-carboxy-4-methyl-5-propyl-2-furanpropionate (CMPF) and urate. Xenobiotics include the mycotoxin ochratoxin (OTA). May also contribute to the transport of organic compounds in testes across the blood-testis-barrier.
Synonyms: hOAT1; OAT1; PAHT; ROAT1
Tractability: Small molecule: an approved drug acts on it; a high-quality ligand is known; it belongs to a druggable protein family. Antibody: UniProt places it where antibodies can reach, with high confidence; its Gene Ontology location is reachable by antibodies, with high confidence; UniProt predicts a signal peptide or a membrane-spanning region. PROTAC: ubiquitination databases record sites on it; a small molecule that binds it is known.
Target class: SLC superfamily of solute carriers; Electrochemical transporter; SLC22 family of organic cation and anion transporters; Transporter
Safety:
Unwanted effects reported when the protein is acted on. In parentheses: how it was acted on, where the effect was seen, and who reports it.
Decrease, Population growth rate (inhibition; proximal tubule; source: AOP-Wiki)
Increased Mortality (inhibition; proximal tubule; source: AOP-Wiki)
Gene: Protein-coding gene on chromosome 11 (62,936,385 to 62,984,967, reverse strand). Ensembl gene ENSG00000197901.
Subcellular location: Basolateral cell membrane; Basal cell membrane
Pathways (Reactome):
Transport of small molecules: Organic anion transport by SLC22 transporters
Gene Ontology:
Molecular function: alpha-ketoglutarate transmembrane transporter activity; antiporter activity; prostaglandin transmembrane transporter activity; protein binding; solute:inorganic anion antiporter activity; transmembrane transporter activity; xenobiotic transmembrane transporter activity; secondary active transmembrane transporter activity
Biological process: alpha-ketoglutarate transport; prostaglandin transport; renal tubular secretion; transmembrane transport; metanephric proximal tubule development; protein homooligomerization; sodium-independent organic anion transport; xenobiotic transport
Cellular component: basal plasma membrane; basolateral plasma membrane; extracellular exosome; plasma membrane; caveola; membrane; protein-containing complex
Genetic constraint (gnomAD): Loss-of-function variants: 40 observed, 55.72 expected, observed/expected ratio (o/e) 0.72, 90% interval 0.56 to 0.93. The upper end of that interval is the gene's LOEUF score, 0.93, which puts it in group 3 of 6, group 1 being the genes least tolerant of losing a copy. Missense variants: 595 observed, 715.32 expected, observed/expected ratio (o/e) 0.83, 90% interval 0.78 to 0.89. Synonymous variants: 290 observed, 301.83 expected, observed/expected ratio (o/e) 0.96, 90% interval 0.87 to 1.06.
Homologues: Orthologues: chimpanzee SLC22A6 (99% identical), macaque SLC22A6 (97% identical), dog SLC22A6 (91% identical), pig SLC22A6 (89% identical), rat Slc22a6 (88% identical), mouse Slc22a6 (85% identical), rabbit SLC22A6 (84% identical), guinea pig SLC22A6 (82% identical), zebrafish oatx (46% identical), zebrafish si:dkey-166k12.1 (33% identical), Drosophila melanogaster Orct2 (29% identical), Caenorhabditis elegans oct-1 (28% identical), and 45 more. Paralogues in human: SLC22A8 (50% identical), SLC22A12 (45% identical), SLC22A11 (42% identical), SLC22A24 (39% identical), SLC22A10 (38% identical), SLC22A9 (36% identical), SLC22A25 (36% identical), SLC22A7 (35% identical), SLC22A13 (34% identical), SLC22A3 (31% identical), SLC22A2 (30% identical), SLC22A1 (30% identical), and 10 more.
Diseases named in the same sentence as SLC22A6 in open-access papers:
SLC22A6 is named in the same sentence as 30 diseases in open-access papers, as found by Europe PMC text mining. Sharing a sentence is not in itself a finding about the gene and the disease. The quoted sentences say what the papers report.
hyperuricemia (8 papers, 2012 to 2022). An abnormally high level of uric acid. "Thus, besides the classic target XO that plays a critical role in uric acid production, transporters, such as organic anion transporter 1 (OAT1, SLC22A6) and urate transporter 1 (URAT1, SLC22A12) in kidney, might be promising targets for treating hyperuricemia." (PMID 31511824, 2019).
chronic kidney disease (3 papers, 2013 to 2022). Impairment of the renal function secondary to chronic kidney damage persisting for three or more months. "For example, the SLC22 genes SLC22A6/OAT1 and SLC22A8/OAT3 participate in the transport of uremic toxins during renal excretion, and accumulation of certain uremic toxins can contribute to the progression of chronic kidney disease." (PMID 36230695, 2022).
renal fibrosis (3 papers, 2018 to 2022). A final common manifestation of a wide variety of chronic kidney diseases characterized by glomerulosclerosis and tubulointerstitial fibrosis. "In agreement with previous studies showing that the inhibition of EMT prevents the loss of RTEC transporters and inhibits inflammation, deletion of RUNX1 promoted SLC22A6 expression and inhibited IL-6 expression in renal fibrosis." (PMID 29759484, 2018). "Obviously, 4-PBA cotreatment indeed inhibited the activation of ER stress and also prevented BV-induced E- to N-cadherin switch and the proteins involved in pro-EMT or renal fibrosis, while restoring the expressions of AQP1, ATP1A1, and SLC22A6 in human renal tubule epithelia." (PMID 35873571, 2022).
gout (2 papers, 2022 to 2024). A condition characterized by painful swelling of the joints, which is caused by deposition of urate crystals. "By PPI analysis we found evidence based on experimental determined that the identified gout causal gene SLC7A7 was strongly correlated with the targets SLC22A6 and SLC22A8 of probenecid." (PMID 39734218, 2024). "Although SLC22A6 and SLC22A8 play a key role in UA transport, the specific mechanism of these two genes in HUA and gout still needs to be further studied, so as to provide new targets for the treatment of HUA and gout." (PMID 35922835, 2022).
kidney cancer (2 papers, 2020). Primary or metastatic malignant neoplasm involving the kidney. "A similar association of SLC22A6 with favourable OS in kidney cancer (KIRC) was recently reported." (PMID 33202946, 2020). "In kidney cancer, SLC22A6, SLC22A7, SLC22A13, SLC25A4, SLC34A1, and SLC44A4 were significantly downregulated." (PMID 32461965, 2020).
breast carcinoma (1 paper, 2014). "SLC22A6 and SLC22A8 mRNAs were not detectable in all analyzed breast cancer cell lines." (PMID 25496233, 2014).
cardiomyopathy (1 paper, 2025). A disease of the heart muscle or myocardium proper. "Different variants in the Solute carrier (SLC) transporters: SLC28A3, SLC22A17, SLC22A7, and SLC22A6 were identified as associated with cardiomyopathy in CCS." (PMID 40413218, 2025).
Hodgkin’s disease (1 paper, 2022). "The drug interaction involving hOAT1 (SLC22A6) and hOAT3 (SLC22A8), responsible for renal tubular methotrexate secretion, has also been described in a Japanese patient with Hodgkin’s disease." (PMID 36015138, 2022).
ischemic stroke (1 paper, 2015). A stroke disorder caused by obstruction of blood flow to the brain, due to thrombotic (local blood clot formation) or embolic (due to a blood clot or other material traveling from another site) event. "Among the downregulated genes, Gpr88, Rgs9, Enthd1, Olr59, P2ry12, Degs2, Pde10a, Neu2, Adora2a, and Slc22a6 were found to demonstrate significant downregulation in pathological phase of ischemic stroke." (PMID 25861363, 2015).
lung carcinoma (1 paper, 2024). "Methotrexate, used in the treatment of several cancers (uterus, breast, and lung carcinomas, certain cancers of the head and neck, and some lymphomas and leukemias), has been described as a substrate of OAT1 (SLC22A6) and OAT2 (SLC22A7)." (PMID 39143954, 2024).
renal carcinoma (1 paper, 2016). A carcinoma arising from the epithelium of the renal parenchyma or the renal pelvis. "We further established the utility of this line for the investigation of renal cancer biology by generating Slc22a6-CreERT2/Vhlfl/fl compound mice which phenocopied previously published models and exhibited no limiting morbidity or mortality." (PMID 26866916, 2016).
cancer (5 papers, 2020 to 2022). A tumor composed of atypical neoplastic, often pleomorphic cells that invade other tissues. "All of the four SLC transporters showed associations only with increased OS rates in cancers, including 1) SLC15A2 (LUAD), SLC22A1 (LIHC), SLC22A2 (KIRC, KIRP), and SLC22A6 (KIRC)." (PMID 33202946, 2020). "Because these are transporters of endogenous metabolites and drugs—and, in the case of SLC22A6, SLC22A8, SLC22A12, established drug targets—these observations are of interest from both the viewpoint of cancer biology and therapeutics." (PMID 36230695, 2022). "Among the various cancers examined, SLC22A6, SLC22A7, SLC22A13, SLC25A4, and SLC34A1 were significantly downregulated, while SLC44A4 showed different expression patterns in different cancers (upregulated or downregulated)." (PMID 32461965, 2020). "We used the Oncomine database to analyze the expression levels of SLC22A6, SLC22A7, SLC22A13, SLC25A4, SLC34A1, and SLC44A4 in various cancers and their normal tissues." (PMID 32461965, 2020). "The expression levels of SLC22A6, SLC22A13, SLC25A4, SLC34A1, and SLC44A4 were significantly correlated with the clinical stage of the cancer." (PMID 32461965, 2020). "Six of these genes were not expressed or were very weakly expressed (ABCC11, SLC22A6, SLC22A7, SLC22A8, SLC22A9, SLCO1B1), and among the other eight genes, only gene ABCG2 showed significant difference in expression in cancer versus adjacent control tissue." (PMID 33917029, 2021). "Similarly, mining the TCGA and GTEx datasets revealed no or very low expression of genes coding hOAT1 (SLC22A6) and hOAT3 (SLC22A8) in most cancer types except for brain and renal tumours (data not shown)." (PMID 31659416, 2020).
tumor (5 papers, 2019 to 2022). "While multiple comparisons had no DE genes in the entire expressed gene list (i.e., Stage III vs. Stage IV), there were 6 DE SLC22 genes in the Tumor Size and Progression comparison in KIRC [SLC22A2, SLC22A5, SLC22A6, SLC22A11, SLC22A12, SLC22A18] (T3 v T4)." (PMID 36230695, 2022). "In KIRC, the stratification of patient data by pathological tumor characteristics revealed the importance of SLC22A2, SLC22A6, and SLC22A12 in disease progression." (PMID 36230695, 2022). "We further utilize bulk RNA-seq data and found a significant upregulation of SOX9, IL32, and SLC22A6 (PT2), and downregulation of SLC22A6/ SLC22A8 (PT1) in tumor compared to adjacent normal tissue, confirming our cell origin hypothesis on PT2 cells." (PMID 36180422, 2022).
SLC22A6 also shares sentences with these, for which no sentence is quoted: glioma (2 papers); IgA nephropathy (2); lupus nephritis (2); membranoproliferative glomerulonephritis (2); metabolic disease (2); acute kidney injury (1); brain edema (1); cholestasis (1); focal glomerular sclerosis (1); glomerulonephritis (1); glutaric aciduria (1); hypophosphatemia (1); Insulin resistance (1); kidney (1); Nephropathy (1); Obesity (1); Ureteral obstruction (1).